IDO1 (indoleamine 2,3-dioxygenase 1)
Diseases named in the same sentence as IDO1 in open-access papers (continued):
Sharing a sentence is not in itself a finding about the gene and the disease.
glioma (continued). "In a preliminary dose-ranging study, oral AT-0174 was determined to elevate tumour tryptophan and significantly attenuate tumour kynurenine in glioma cell-based xenograft malignancies that over-expressed IDO1 and TDO2." (PMID 39048947, 2024). "In glioma tissue sections, it was observed that the expression levels of IDO1, VEGFA, and CD34 were positively correlated with the pathological grades, with expression levels in grade III/IV glioma patients significantly higher than in patients of lower grade." (PMID 39065567, 2024). "Consistent with what we observed in glioma cells, IDO1 overexpression also upregulates VEGFA through GCN2 activation in mice." (PMID 39065567, 2024). "We found that in glioma cells, IDO1 overexpression only activated the GCN2 pathway and upregulated VEGFA expression if it caused a drastic decrease in Trp levels." (PMID 39065567, 2024). "Herein, we aim to clarify the potential role of IDO1 in glioma angiogenesis and the mechanism behind it." (PMID 39065567, 2024). "IDO1 overexpression in glioma cells impedes an effective immune response through increased apoptosis of CD8+ T cells and by converting naïve T cells into inducible immunosuppressive Tregs." (PMID 38473776, 2024). "IDO1 expression is increased in many human tissues, and it is overexpressed in the majority of cancers (90% of glioma cells) by proinflammatory cytokines, such as IFN-γ and TNF-α, or in response to interaction with tumor-infiltrating T or NK cells." (PMID 38473776, 2024). "In this study, we investigate the mechanism by which IDO1 induces angiogenesis in glioma and aim to provide new evidence supporting dual IDO1 and VEGFA blockade as a viable anti-tumor therapeutic strategy." (PMID 39065567, 2024). "The chemokines CCL22 and IDO1 are other factors known to promote recruitment and activation of Tregs in gliomas." (PMID 38275375, 2023). "IDO1 shows only a weak expression in the adult CNS but an enhanced expression in many tumors such as gliomas." (PMID 38275375, 2023). "All six of the most critical ICGs that were examined, including CD274, CTLA4, HAVCR2, IDO1, PDCD1, and PDCD1LG2, exhibited a significant positive correlation with the risk scores in glioma samples." (PMID 36845382, 2023). "Indoleamine 2,3-dioxygenase 1 (IDO1) also promotes immunosuppression and immunotolerance in gliomas, as well as increasing their malignancy." (PMID 37830595, 2023). "Upregulation of some immune checkpoints, such as CD27, CD274 (PD-L1), CTLA4, IDO1, and PDCD1 (PD-1), were reported to be associated with poor survival and recurrence in gliomas." (PMID 35874989, 2022). "Tryptophan-2,3-dioxygenase is expressed exclusively by high-grade gliomas and is of the same function as IDO1." (PMID 36295820, 2022). "A durable survival benefit was achieved utilizing combinatorial blockade against CTLA-4, PD-L1 and indoleamine 2,3 dioxygenase 1 (IDO) in glioma-bearing mice models." (PMID 35428347, 2022). "IDO-1 is expressed in many primary and metastatic tumors such as lung, breast, brain, and gliomas, and it is now considered as a target for potential immunotherapy." (PMID 35328349, 2022). "A recent glioma immune escape gene signature analysis for mice reconfirmed the roles of IDO1 and arginase-1." (PMID 36295820, 2022). "Like IDO-1, high expression of TDO-2 was also associated with worse prognosis, such as in low-grade glioma, clear cell renal cancer, papillary renal cancer, acute myeloid leukemia, mesothelioma, and testicular germ cell tumor." (PMID 34367262, 2021). "Comprehensive studies on cancer patients proved that expression and activity of IDO1 is strongly correlated with pathological grades of glioma." (PMID 34959693, 2021). "As an immune checkpoint, the Trp metabolism of glioma cells also limited the infiltration of CTLs through IDO1." (PMID 34211978, 2021).
glioma (continued). "Intriguingly, other immunological indices including PD‐1, CTLA4, and IDO‐1, which are closely related to glioma progression, were also found to be abundantly expressed in the high‐risk score group." (PMID 33969928, 2021). "In glioma, IDO1/TDO was shown to account for Kyn release and subsequent AhR-activation mediated cell motility via the expression of aquaporin 4 (AQP4)." (PMID 33451095, 2021). "In both clinical studies and preclinical murine glioma models, tumors with high expression levels of IDO1 were infiltrated with more FoxP3+ regulatory T cells." (PMID 34222022, 2021). "Gliomas are adept at recruiting regulatory T cells to the microenvironment by over-production of factors such as indoleamine 2,3 -dioxygenase-1 (IDO-1)." (PMID 34771532, 2021). "Using a glioma cell line, we found that both IDO1 and TDO contributed to the production of Kyn, which upregulated AhR expression and regulated the migration and invasion of glioma cells." (PMID 32296044, 2020). "The expression of IDO1/TDO was positively correlated with the expression of AQP4, which was associated with migration and invasion in glioma." (PMID 32296044, 2020). "Then, the therapeutic efficacy of the IDO1/TDO dual inhibitor RY103 was examined in GL261 orthotopic glioma mice." (PMID 32296044, 2020). "Our study not only provides an improved understanding of the relationship between Trp catabolism and gliomas but also supports anti-glioma drug development targeting IDO1/TDO." (PMID 32296044, 2020). "Using GL261 orthotopic glioma mice, the therapeutic effects of the IDO1/TDO dual inhibitor RY103 were confirmed." (PMID 32296044, 2020). "The results indicated that IDO1/TDO expression was negatively correlated with the prognosis of patients with gliomas." (PMID 32296044, 2020). "In animal models of glioma, the combination of IDO1 and PD-1 inhibitors prolongs the survival time of animals." (PMID 33552086, 2020). "We also analyzed IDO1 expression in a data set where glioma stem cells and adult neural stem cells were compared (GEO accession ID GSE31262)." (PMID 32469935, 2020). "Using the U87MG glioma cell line, we found that IDO1/TDO accounted for the production of Kyn, which activated AhR to promote cell motility via the Kyn–AhR–AQP4 signaling pathway and modulated the cell area and cytoskeleton." (PMID 32296044, 2020). "In summary, the IDO1/TDO–Kyn–AhR–AQP4 signaling pathway plays an important role in glioma cell migration and invasion." (PMID 32296044, 2020). "Our study showed that the GL261 orthotopic glioma mouse model was applicable for the pharmacodynamic study of IDO1/TDO inhibitors." (PMID 32296044, 2020). "In this study, RY103, an IDO1/TDO dual inhibitor, showed excellent therapeutic efficacy via downregulating the IDO1/TDO–Kyn–AhR–AQP4 signal pathway in GL261 orthotopic glioma mice." (PMID 32296044, 2020). "IDO1 is known to be overexpressed in many tumors – including gliomas – with both tumor and stromal cells contributing to IDO1 activity." (PMID 32477324, 2020). "Given that IDO2 expression was not correlated with the pathologic grades of glioma, it was deduced that the expression and activity of IDO1/TDO increased with the pathologic grades of glioma, and both IDO1 and TDO were involved in the malignancy of glioma." (PMID 32296044, 2020). "We wanted to use human glioma cells to examine the effects of IDO1/TDO on cell migration and invasion." (PMID 32296044, 2020). "The upregulation of IDO-1 mRNA levels is positively correlated with the glioma grade, while it has an inverse relationship with the survival rate in patients with gliomas." (PMID 33330446, 2020). "In this GL261 glioma cell line xenograft model, only triple combination of irradiation, PD-1 inhibition, and IDO1 inhibition achieved durable responses." (PMID 31905723, 2019).
glioma (continued). "In previous studies, PD-L1 (programmed death-ligand 1), TIM3 (T-cell immunoglobulin mucin-3), and IDO1 (indoleamine 2,3 dioxygenase 1) transcript levels were strongly correlated with immune responses and prognosis in gliomas." (PMID 29764444, 2018). "Expression of IDO1 (indoleamine 2, 3-dioxygenase 1), tryptophan metabolic enzyme, increases the recruitment of regulatory T cells and negatively impacts survival in glioma cells." (PMID 30407923, 2018). "Our qRT-PCR analyses further substantiate and corroborate these findings revealing that IDO-1 expression in glioma cells was significantly up-regulated after 24 hours of IFN-γ stimulation compared to unstimulated glioma cells." (PMID 25415278, 2014). "This is especially valuable because IDO1 is currently evaluated for the treatment of glioma." (PMID 39378431, 2025). "In summary, our study demonstrated that IDO1 contributed to glioma angiogenesis by causing Trp depletion in the TME, and IDO1 inhibitor RY103 might be a potential therapeutic choice against glioma." (PMID 39065567, 2024). "Our result by bioinformatic analysis not only showed the correlation between IDO1 expression and pathological grade of glioma as well as poor prognosis of the patients but also revealed that the expression of IDO1 positively correlates with those of angiogenesis-related genes." (PMID 39065567, 2024). "We sought to explore if IDO1 modulated glioma angiogenesis via activation of the GCN2 pathway." (PMID 39065567, 2024). "Our study also investigated the role of the GCN2 pathway during angiogenesis, but rather than GCN2 protein itself or other amino acids, we instead focused on the activation of the pathway by Trp depletion, as it was closely affiliated with overexpressed IDO1 in glioma." (PMID 39065567, 2024). "The effect of IDO1 inhibitors on glioma, such as INCB024360, has been drawing attention." (PMID 39065567, 2024). "The immunosuppressive subgroup characterized by the high expression of indoleamine 2,3-dioxygenase 1 (IDO1;) and low expression of MHC class II molecule (HLA-DR) was identified in rGBMs as one sort of mononuclear phagocytes, glioma-associated microglia, and macrophages (GAMs)." (PMID 35805138, 2022). "Furthermore, glioma patients with upregulated intratumoral IDO1 expression have shorter OS when compared to those with intermediate and downregulated IDO expression (44.3 vs. 34 vs. 24.9 months)." (PMID 36011015, 2022). "Furthermore, expression of regulators of mt-rRNA modification was associated with major moieties associated with immune checkpoints in glioma, especially PD-L1, PD-1, CD80, CD274, TIM3, and IDO1." (PMID 34566979, 2021). "IDO1 is widely expressed in gliomas and is predictive of a poor prognosis in glioma patients." (PMID 34659216, 2021). "Interestingly, the combination of IFNγ and TMZ that mimics the in vivo situation led to similar or even stronger IDO1 upregulation compared to IFNγ alone in two out of four glioma samples." (PMID 32117235, 2020). "Although the aberrant activation of KP and expression patterns of the first rate-limiting KP enzyme in gliomas have been previously reported, the systemic and comprehensive studies of the expression, activity, and individual function of IDO1 and its isozymes in gliomas are very limited." (PMID 32296044, 2020). "Our in vivo study confirmed that inhibition of IDO1/TDO could suppress the malignancy of glioma by blocking the IDO1/TDO–Kyn–AhR–AQP4 signaling pathway." (PMID 32296044, 2020). "Our data showed that the Kyn/Trp ratio and IDO1 expression were positively correlated with the pathologic grades of glioma, which suggested an indispensable function of IDO1 in the pathological process of gliomas." (PMID 32296044, 2020). "Glioma stem cells showed a markedly increased IDO1 expression (Log2FC = 2.73, p = 0.005)." (PMID 32469935, 2020). "IDO1 was differently expressed by most glioma samples (11/13) analyzed." (PMID 32117235, 2020).
glioma (continued). "In addition, the effect of IDO1 on the motility of glioma cells and the mechanism behind the effect needs further elucidation." (PMID 32296044, 2020). "Thus, the IDO1/TDO–Kyn–AhR–AQP4 signaling pathway is a novel mechanism for understanding the malignancy of gliomas." (PMID 32296044, 2020). "Furthermore, the therapeutic efficacy of a dual inhibitor of IDO1/TDO in GL261 orthotopic glioma mice was examined." (PMID 32296044, 2020). "IDO-1 was expressed in all glioma samples when untreated and treated." (PMID 25415278, 2014). "IDO-1 up-regulation and induction in glioma cells may function to deplete TRP from the tissue microenvironment and accumulate KP-derived toxic metabolites, which may ultimately suppress T-cell proliferation." (PMID 25415278, 2014). "We compared the mRNA levels of IDO1 among high-grade (GBM) and low-grade (LGG) glioma downloaded from The Cancer Genome Atlas (TCGA) database, and health tissues (normal) downloaded from the Genotype-Tissue Expression (GTEx) database to illustrate the biological role of IDO1 in GBM progression." (PMID 39863603, 2025). "This may be attributed to the function of IDO1 in angiogenesis and malignancy of glioma." (PMID 39065567, 2024). "Given that IDO1 can induce immunosuppressive immune cells, including Treg cells in TME, and anti-VEGF therapy correlates to the increase in IDO1 expression, it is worth exploring whether the addition of IDO1 inhibitors improves the performance of anti-angiogenic drugs against glioma." (PMID 39065567, 2024). "In gliomas, T cell tolerance can result from peripheral deletion of T cells through Fas-L-mediated apoptosis or through the immunosuppressive effect of Tregs, which in turn is induced by upregulated expression of IDO1 and the signal transducer and activator of transcription 3 (STAT3)." (PMID 38275375, 2023). "Moreover, we determined that IDO1, which catabolizes tryptophan into the immunosuppressive metabolite kynurenine, is expressed at significantly higher levels in MDMs and MG isolated from pTRT cell-high BrM than those from pTRT cell-low BrM or glioma." (PMID 37217652, 2023). "In addition, IDO1 expression has been associated with an immunosuppressive TME, infiltration of tumor-associated macrophages (TAMs) and regulatory T lymphocytes (Tregs), which results in a poor survival rate in glioma patients." (PMID 36986469, 2023). "It was not until recently that the role of TDO in cancer was appreciated, when emerging evidence showed that TDO, but not IDO1, is the central Trp-degrading enzyme in human glioma cells, and that the TDO–AhR pathway was associated with malignant progression and poor survival for this tumor." (PMID 35847038, 2022). "Thus IDO1 is becoming an attractive target of immunotherapy in grade IV gliomas, especially GBM." (PMID 35135556, 2022). "Moreover, overexpression of IDO1 correlates with poor prognosis in patients with glioma." (PMID 34959693, 2021). "In addition, all glioma samples demonstrated constitutive IDO-1 expression." (PMID 25415278, 2014). "Key enzymes such as indoleamine 2,3-dioxygenase (IDO1) and tryptophan 2,3-dioxygenase (TDO2) are commonly overexpressed in human glioma cells, resulting in elevated production of kynurenine." (PMID 40843669, 2025). "Recent studies have demonstrated that IL4I1 activates AhR more potently than IDO1 and TDO2, generating indole metabolites and quinolinic acid that promote tumor progression in gliomas and leukemia by enhancing cancer cell motility and suppression immunity." (PMID 40559961, 2025). "Similar results were observed by analyzing IDO1 expressions between patients with GBM and LGG from the Chinese Glioma Genome Atlas (CGGA) database." (PMID 39863603, 2025). "IDO1 and TDO contribute to increased kynurenine production and AhR expression, which further regulate glioma cell migration and invasion." (PMID 40075568, 2025).
glioma (continued). "Immunohistochemistry staining was employed to determine the expression levels of IDO1, VEGFA, and CD34 in paraffin-embedded tissue sections obtained from 5 non-glioma tissue donors and 13 glioma tissue donors." (PMID 39065567, 2024). "Mice subcutaneously bearing IDO1 stable overexpressing (IDO1-SOE) and wild-type GL261 subcutaneous glioma-bearing mice (WT) were constructed and compared." (PMID 39065567, 2024). "IDO1 inhibitor RY103 showed positive anti-tumor efficacy, including the anti-angiogenesis effect and upregulation of natural killer cells in GL261 glioma-bearing mice." (PMID 39065567, 2024). "We also found that the HIS subtype had the highest expression of several immune checkpoints (particularly IDO1, CD274 and PDCD1LG2), it means that glioma samples from HIS subtype tend to be immunosuppressed." (PMID 38613347, 2024). "Bioinformatic analyses showed that the expressions of IDO1 and angiogenesis markers VEGFA and CD34 were positively correlated and increased with pathological grade in glioma." (PMID 39065567, 2024). "Lastly, we determined that IL4I1, IDO1, and AHR are significantly higher in GBMs compared to low-grade gliomas." (PMID 38937431, 2024). "It has been shown that therapeutic inhibition of IDO1, CTLA-4, or PD-L1 significantly reduced the number of tumor-infiltrating T cells and significantly prolonged the survival in a mouse model of glioma." (PMID 39502752, 2024). "Overexpression of systemic immunosuppressive soluble factors by glioma cells, such as PTGS2 (rate-limiting step catalyzed by COX-2), TGFB1, IDO1, and IL-10, were also investigated at the transcriptional level." (PMID 37322408, 2023). "Other checkpoint proteins of importance in glioma biology include the immunomodulator B7-H3 (CD276) and the tryptophan-degrading enzyme indoleamine-2,3-dioxygenase (IDO1)." (PMID 38275375, 2023). "Our study found that several immune checkpoints (BTLA, CD200R1, PD-L1, B7-H3, CD70, CTLA4, IDO1, and PD1) in patients with CDC42 high expression glioma were upregulated compared to the CDC42 low expression group." (PMID 37476838, 2023). "We found that TPM4 is related to the molecular targets of glioma, such as CD160, IDO1, IL10, KDR, PVRL2, and TGFB1." (PMID 36639743, 2023). "Other than PD-1 and CTLA-4, indoleamine 2,3-dioxygenase-1 (IDO-1) as well as T cell immunoglobulin and mucin domain 3 (TIM-3) have recently come to the forefront in glioma immunotherapy." (PMID 37046685, 2023). "In general, most immune checkpoints (including PD-1, TIM-3, CD96, PDCD1, IDO1, PDCD1LG2, and CTLA-4) were highly expressed in glioma cells." (PMID 36778644, 2023). "In our study, Siglec15 was broadly and positively correlated with immune checkpoints that have been reported as potential biomarkers of glioma, such as PD1, PDL1, PDL2, Lag3, CTLA4, TIGIT, CD276 (B7-H3), IDO1 and CD47." (PMID 37325664, 2023). "We analyzed the TCGA database to examine IL4I1, IDO1, and AHR expression and their contribution to glioblastoma and low-grade glioma (LGG) patients’ clinical outcome." (PMID 37986881, 2023). "Based on the TCGA and CGGA datasets, we proved that PTX3 positively correlated with CD276, CD274, PDCDL1LG2, HAVCR2, CD80, IDO1, and PDCD1 in pan‐glioma, GBM, and LGG." (PMID 35855654, 2022). "Augmented production of Trp and arginine, and elevated expression of metabolic enzymes IDO1, ASL and ARG2 in glioma cells were accompanied by increased infiltration of Tregs." (PMID 34211978, 2021). "In a glioblastoma cell line-U87MG, inhibition of IDO1/TDO with RY103, Kyn-AhR mediated proliferation of glioma cells reduced that suggest Kyn-AhR involvement in pathology of glioblastomas." (PMID 34205235, 2021). "Additionally, changes in AhR and AhR target gene levels have been linked to increased IDO1 and TDO2 levels in glioblastoma cells pointing to the fact that increased IDO-activity might promote AhR-mediated changes in glioma cells that enable immune escape and malignant potential." (PMID 34819875, 2021).